RTEL1 (regulator of telomere elongation helicase 1)
Diseases named in the same sentence as RTEL1 in open-access papers (continued):
Sharing a sentence is not in itself a finding about the gene and the disease.
glioma (continued). "Altogether, our findings supported the strong tumorigenic role of RTEL1 in glioma." (PMID 38532312, 2024). "The risk of tumorigenesis or cancer predisposition due to RTEL1 mutations is not only observed in the case of HHS or DC, but interestingly, it has also been connected to the predisposition for brain malignancies like gliomas, astrocytomas, and glioblastomas." (PMID 39240887, 2024). "In conclusion, our results suggested that RTEL1 promotes glioma tumorigenesis through JNK/ELK1 cascade and indicate that RTEL1 may be a prognostic biomarker in gliomas." (PMID 38532312, 2024). "In order to investigate the biological role of RTEL1 in glioma." (PMID 38532312, 2024). "Several studies have demonstrated the relationship between RTEL1 variants and the inherited susceptibility to glioma, specific to,19 or regardless of its histological subtypes." (PMID 36253342, 2023). "In addition to the integrated phenotypic and genotypic features of glioma, many genetic studies have found that common inherited variants near several genes (TERC, TERT, EGFR, CDKN2B, PHLDB1 and RTEL1) are associated with increased risk of adult glioma." (PMID 30462709, 2018). "While dysregulation of the telomere gene RTEL1 has traditionally been assumed to represent the functional basis of the 20q13.33 locus, the glioma risk SNP does not map to the locus associated with telomere length." (PMID 29460007, 2018). "Among the associated inherited risk variants, RTEL1 variants were found to be associated with risk of glioma regardless of molecular alterations." (PMID 30462709, 2018). "Because the association between glioma risk and LTL remained significant even after excluding the TERC, TERT and RTEL1 SNPs from the LTL calculations, it is unlikely that the association observed in our data could be entirely attributable to pleiotropy." (PMID 26646793, 2015). "In conclusion, our comprehensive analysis of tSNPs suggests that the genotypes of “GG” of rs6010620 and “CC” of rs2297440 (rs6010620 and rs2297440) in the RTEL1 gene, together with two haplotypes of GCT and ATT, were identified to be associated with glioma development." (PMID 23683922, 2013). "Thus, we attempted to determine whether ROS production was detected when RTEL1 knockdown in glioma cells." (PMID 38532312, 2024). "Furthermore, RTEL1 knockdown dramatically promoted glioma cell apoptosis relative to the si-N.C." (PMID 38532312, 2024). "In addition, in vivo studies also revealed the oncogene role of RTEL1 in glioma." (PMID 38532312, 2024). "A case-control study recruited 855 high-grade glioma patients from four different geographic regions of the US and belonging to five inherited glioma risk variants: 5p15.3 (TERT), 8q24.21 (CCDC26/MLZE), 9p21.3 (CDKN2B), 11q23.3 (PHLDB1/DDX6) and 20q13.3 (RTEL1)." (PMID 30909395, 2019). "However, association between RTEL1 SNPs, including coding variants, and risk of gliomas is not obvious." (PMID 30462709, 2018). "Collectively, our results showed that RTEL1 significantly facilitated phosphorylation of JNK signaling and the downstream transcription factor ELK1 in the tumorigenesis of glioma cells." (PMID 38532312, 2024). "We found that RTEL1 knockdown significantly inhibited cell proliferation and colony formation of glioma cells compared to the negative control, which demonstrated the carcinogenic role of RTEL1 in glioma cells." (PMID 38532312, 2024).
glioma (continued). "RTEL1 expression is modulated by this SNP in isocitrate dehydrogenase I wild‐type glioma and during early brain development but not in normal adult brain tissues." (PMID 36253342, 2023). "Consistent with this, rs3761124 correlated with altered expression of RTEL1 in IDH1 wild‐type glioma and during early brain development but not in the CMC brain tissues." (PMID 33169458, 2021). "RTEL1‐TNFRSF6B is a noncoding, readthrough transcript that is subject to NMD, but it is currently unclear how a change in mRNA decay will affect glioma development." (PMID 33169458, 2021). "Therefore, STMN3 is a consistent eQTL for rs3761124 in early neurological development, in the normal adult brain and in glioma or during gliomagenesis, whereas the RTEL1 expression correlated with rs3761124 only during early neurological development and in IDH1 wild‐type glioma." (PMID 33169458, 2021). "Our data also implicate RTEL1 and GMEB2 in glioma, but their role may be more context‐specific." (PMID 33169458, 2021). "In glioma, genome-wide association studies have identified common genetic variations in 7 genes that increase glioma risk (TERT, EGFR, CCDC26, CDKN2A, CDKN2B, PHLDB1 and RTEL1) but BRCA1 is not among them and there is no known association between BRCA1 gene and glioblastoma multiforme (GBM)." (PMID 25880076, 2015).
dyskeratosis congenita (25 papers, 2013 to 2025). Dyskeratosis congenita (DC) is a rare ectodermal dysplasia that often presents with the classic triad of nail dysplasia, skin pigmentary changes, and oral leukoplakia associated with a high risk of bone marrow failure (BMF) and cancer. "Germline mutations in the RTEL1 gene have been clinically associated with Hoyeraal-Hreidarsson syndrome, a more severe version of Dyskeratosis Congenita." (PMID 39240887, 2024). "In humans, mutations in the RTEL1 gene have been proven to cause a rare genetic hereditary disease called Dyskeratosis congenita (DC) and its severe form Hoyeraal–Hreidarsson syndrome (HHS)." (PMID 39240887, 2024). "AR and, more rarely, AD mutations in RTEL1 are associated with dyskeratosis congenita, and AD variants in RTEL1 have also been associated with idiopathic pulmonary fibrosis, even with a late or very late onset." (PMID 36880831, 2023). "A severe multisystem bone-marrow-failure syndrome, dyskeratosis congenita, is linked to mutations in RTEL1, a helicase that processes telomeric G4-DNA." (PMID 34139671, 2021). "In humans, Rtel1 is highly expressed in several types of tumor tissues and specific mutations in Rtel1 have been attributed to dyskeratosis congenita and Hoyeraal-Hreidarsson syndrome." (PMID 25147792, 2014). "published a paper entitled “Germline mutations of regulator of telomere elongation helicase 1, RTEL1, in dyskeratosis congenita” (Hum." (PMID 23453664, 2013). "Mutations in various domains of RTEL1, including the helicase domain, have been associated with telomere biology disorders such as dyskeratosis congenita, Hoyeraal–Hreidarsson syndrome, pulmonary fibrosis, bone marrow failure syndrome, myeloid neoplasms, and increased susceptibility to brain tumors." (PMID 39156922, 2024). "RTEL1 mutations have been associated with dyskeratosis congenita and Hoyeraal–Hreidarsson syndrome." (PMID 35783634, 2022). "The RTEL1 helicase, mutated in Dyskeratosis congenita (DC) or its more severe form Hoyeraal-Hreidarsson syndrome (HHS), and the DDX11 helicase mutated in Warsaw Breakage syndrome (WBS) have most recently joined the group of clinically relevant Fe-S DNA helicases." (PMID 32120966, 2020). "Mutations in DKC1 and RTEL1, result in dyskeratosis congenita (DC), telomeropathies with accelerated shortening or damage of telomeres and bone marrow failure." (PMID 36248828, 2022). "The RTEL1 c.3028C>T sequence variant was previously associated with IPF, dyskeratosis congenita and Hoyeraal-Hreidarsson Syndrome." (PMID 31910222, 2020). "In humans, germline homozygous RTEL1 mutations result in severe telomere-related disorders, including Dyskeratosis congenita (DKC) and Hoyeraal-Hreidarsson syndrome (HHS), while heterozygous RTEL1 mutations are associated with familial pulmonary fibrosis with no hematologic phenotypes." (PMID 40087886, 2025). "Likewise, in the Fe–S helicase RTEL1, missense variants such as p.Arg1264H is impair T-loop disassembly, leading to defective telomere replication and the critically short telomeres that underlie Dyskeratosis Congenita (DC)." (PMID 41302153, 2025). "In patients with Hoyeraal–Hreidarsson syndrome (a severe variant of dyskeratosis congenita), mutation affects the RTEL1 C4C4 metal-binding motif, so that RTEL1 no longer binds to TRF2, and this RTEL1 variant fails to rescue the telomere loss and the telomere circles induced by RTEL1 deletion." (PMID 28350373, 2017). "This work provides an example of the importance of the careful balance of PAR synthesis and degradation and also provides an attractive therapeutic option for RTEL1-mediated telomeropathies, such as Hoyerall–Hreidarsson syndrome (HHS) and Dyskeratosis congenita (DKC)." (PMID 35348914, 2022).
pulmonary fibrosis (16 papers, 2017 to 2025). Chronic progressive interstitial lung disorder characterized by the replacement of the lung tissue by connective tissue, leading to progressive dyspnea, respiratory failure, or right heart failure. "RTEL1 ultra-rare variants can be considered as a predictive marker of COVID-19 severity, as well as a marker of pathological evolution for pulmonary fibrosis in the post-COVID phase." (PMID 37328761, 2023). "RTEL1 ultra-rare variants can be considered as a predictive marker of COVID-19 severity, as well as a marker of pathological evolution in pulmonary fibrosis in the post-COVID phase." (PMID 37328761, 2023). "Pathogenic variants in RTEL1 gene, encoding for a helicase that regulates telomere elongation, have been identified in rare interstitial pneumoniae, called Idiopathic Pulmonary Fibrosis (IPF)." (PMID 37328761, 2023). "Variants in NAF1, TERT, TERC, PARN, and RTEL1 have been associated with clinical presentations of pulmonary fibrosis, liver disease, or bone marrow failure in middle or later age." (PMID 35359366, 2022). "Recently an RTEL1 c.2257C>T variant resulting in an amino acid substitution at the same codon as our c.2258G>A variant was described in a patient with pulmonary fibrosis." (PMID 31910222, 2020). "More studies brought up that the mutation of RTEL1 had been linked to dyskeratosis congenital, Hoyeraal-Hreidarsson syndrome, pulmonary fibrosis, myelodysplastic syndrome, and lung cancer and even rheumatoid arthritis-associated interstitial lung disease." (PMID 30159339, 2018). "However, heterozygous LoF variants in RTEL1 results in a very late‐onset pulmonary fibrosis, and the gene itself is under modest evolutionary constraint according to gnomAD data." (PMID 38653581, 2024). "Finally, their decreased diffusion lung capacity for carbon monoxide after six months of COVID-19 suggests that RTEL1 variants can contribute to the development of SARS-CoV-2-elicited lung fibrosis." (PMID 37328761, 2023). "Finally, the decreased DLCO after six months of COVID-19 suggests that RTEL1 variants can contribute to the development of lung fibrosis following COVID-19." (PMID 37328761, 2023). "Moreover, RTEL1-mutated pulmonary fibrosis families display a precocious onset of pulmonary disease, concomitant liver pathologies, and in some cases early reversible neutropenia." (PMID 37328761, 2023). "RTEL1 is linked to pulmonary fibrosis, TRIM34 plays a role in restricting HIV-1 infection, PPP2R2A is a potential therapeutic target, and IRF7 shows high expression in certain COVID-19 patients, underlining the diverse implications of these genes in the context of SARS-CoV-2 infection." (PMID 38681774, 2023). "In addition, heterozygous missense variants in RTEL1 have been identified in association with idiopathic pulmonary fibrosis, reported in 10 pedigrees." (PMID 28507545, 2017). "Rare telomere-maintenance gene pathogenic variants, such as TERT, TERC, RTEL1, and PARN, are principal causes of pulmonary fibrosis and familial pulmonary fibrosis and are associated with shorter telomeres, earlier disease onset, and poor outcomes." (PMID 41465275, 2025). "A subset of patients with pulmonary fibrosis (173/204) were previously evaluated for qualifying variants in telomere-related genes in TERT, RTEL1, or PARN." (PMID 37904125, 2023). "PGV in genes such as RTEL1, TINF2, and ACD are associated with autosomal dominant (heterozygous) risks for pulmonary fibrosis or bone marrow failure as well as autosomal recessive (homozygous or compound heterozygous) risks for HH." (PMID 35359366, 2022). "Indeed, heterozygous variants have been detected in familial forms of pulmonary fibrosis involving TERT (∼15%), RTEL1 (5–10%), PARN (∼5%), and TERC (∼3%)." (PMID 36833253, 2023).
pulmonary fibrosis (continued). "Notably, majority of the cases reported with solely heterozygous RTEL1 mutations are found to be associated with telomeropathy-related lung fibrosis and familial pulmonary fibrosis with no immunologic or hematologic phenotypes." (PMID 28507545, 2017).
Hoyeraal-Hreidarsson syndrome (12 papers, 2013 to 2025). Hoyeraal-Hreidarsson syndrome (HHS) is a very rare X-linked recessive disorder considered to be a severe variant of dyskeratosis congenita characterized by intrauterine growth retardation, microcephaly, cerebellar hypoplasia, progressive combined immune deficiency and aplastic anemia. "RECQL4 (Rothmund-Thomsun syndrome) and RTEL1 (Hoyeraal-Hreidarsson Syndrome), deficiencies impart increased risks of cancer cancer, autoimmunity and premature ageing." (PMID 31287417, 2019). "Besides other biallelic mutations in RTEL1 lead to severe telomere biology disorder called Hoyeraal Hreidarsson syndrome." (PMID 38653581, 2024).
lung carcinoma (8 papers, 2016 to 2023). "Several GWAS and candidate gene studies have identified that RTEL1 variants are associated with cancer genetic susceptibility, including lung cancer, breast cancer, gastric cancer, colorectal cancer, and esophageal cancer." (PMID 38001404, 2023). "The study identified RNASET2, SECISBP2L,NRG1, CHRNA2, OFBC1 and RTEL1 as candidate genes associatedwith lung cancer." (PMID 33959694, 2020). "In addition, RTEL1 rs2738780, rs7261546 and rs6062299 were found to be associated with lung cancer development in Han Chinese populations in case-control studies." (PMID 31762827, 2019). "In the context of lung cancer, genetic variants at several loci have been associated with both LTL and lung cancer risk, including variants near the TERT, TERC, OBFC1, and RTEL1 genes, fundamental to telomere length maintenance." (PMID 37079368, 2023). "RTEL1 (regulator of telomere elongation helicase 1; OMIM 608833) gene polymorphisms were linked to lung cancer (LC) susceptibility in a cancer genome-wide association study (GWAS) Here, we assessed whether seven previously reported RTEL1 polymorphisms influenced LC risk in Han Chinese population." (PMID 27765928, 2016).
glioblastoma (7 papers, 2012 to 2024). The most malignant astrocytic tumor (WHO grade IV). "RTEL1 rs3787098 allele frequency has been associated with glioblastoma risk in the Chinese Han population." (PMID 27765928, 2016). "Polymorphism in the RTEL1 gene was associated with glioblastoma survival." (PMID 23683922, 2013).
Immunodeficiency (6 papers, 2013 to 2023). Failure of the immune system to protect the body adequately from infection, due to the absence or insufficiency of some component process or substance. "Based on the diverse evidence discussed in this section, we propose that inflammation and immune deficiency induced by RTEL1 deficiency can promote tumorigenesis." (PMID 36253342, 2023). "This study further implicates RTEL1 in the etiology of DC/HH and immunodeficiency, and identifies the first known homozygous autosomal recessive disease-associated mutation in RTEL1." (PMID 24009516, 2013). "The classical mucocutaneous triad pinpointing toward DC (leukoplakia, dystrophic nails, and reticular pigmentation) may be completely missing or only partially present even years after onset of BMF and immunodeficiency in RTEL1-deficient patients." (PMID 28507545, 2017).
bone marrow failure (5 papers, 2015 to 2023). "Bone marrow failure is the most common feature in patients with DC and the predominant cause of death and is a common single clinical manifestation in patients with telomere biology gene mutations, especially in the TERT, TERC, and RTEL1 genes." (PMID 36311538, 2022).
colorectal cancer (5 papers, 2019 to 2023). A primary or metastatic malignant neoplasm that affects the colon or rectum. "In the TCGA database, the differential expression of RTEL1 mRNA in colorectal cancer was higher than normal control with statistical significance (p < 0.001)." (PMID 35783634, 2022). "Furthermore, previous studies have revealed overexpression of the RTEL1 genomic locus in several cancers such as breast, lung, esophagus, gastric, and colorectal cancer (Muleris, Almeida, Gerbault‐Seureau, Malfoy, & Dutrillaux, 1995)." (PMID 30623606, 2019). "However, no reports implied the direct or indirect associations of RTEL1 with sporadic colorectal cancer or CAC." (PMID 35184406, 2022). "The significant differential expression of RTEL1 in colorectal cancer and normal control in TCGA indicates that RTEL1 may play a role in the progression of malignancy, while its contribution to IGN or adenocarcinoma that developed from IGN is unclear and worth investigating." (PMID 35783634, 2022).
coronary heart disease (5 papers, 2016 to 2024). "Furthermore, genome-wide association studies of adult leukocyte TL (LTL) identified 7 single-nucleotide variations (ACYP2, NAF1, OBFC1, RTEL1, TERC, TERT, ZNF208) linked with LTL that mutually project towards an increased risk for coronary artery disease." (PMID 35930283, 2022). "Finally, the RTEL1 gene plays a protective role against coronary heart disease." (PMID 38293941, 2024).
idiopathic pulmonary fibrosis (5 papers, 2018 to 2023). Idiopathic pulmonary fibrosis (IPF) is a nonneoplastic pulmonary disease that is characterized by the formation of scar tissue within the lungs in the absence of any known cause. "Sequence variants in genes for surfactant proteins (SFTPC, SFTPA1, SFTPA2, ABCA3), polymorphisms in MUC5B or TOLLIP, and mutations in telomere genes (TERT, TERC, PARN, and RTEL1) are associated with an increased risk of idiopathic pulmonary fibrosis (IPF)." (PMID 36864460, 2023).